MX1 (MX dynamin like GTPase 1)
Diseases named in the same sentence as MX1 in open-access papers (continued):
Sharing a sentence is not in itself a finding about the gene and the disease.
myeloproliferative disease (7 papers, 2009 to 2024). "Conditional Kras A146T expression in HSC (Mx1-Cre) lead to myelodysplastic syndrome/myeloproliferative neoplasm (MDS/MPN) with the expansion of immature myeloid cells in the BM and spleen." (PMID 35158933, 2022). "Induction of KrasG12D expression in the hematopoietic system via Mx1-Cre leads to a rapid and highly penetrant myeloproliferative disease (MPD) but not overt AML." (PMID 35756660, 2022). "The Mx1-cre kras+/G12D mouse model mirrors several key features of this disease and has been used extensively to determine the utility and mechanism of small molecule therapeutics in the context of RAS-driven myeloproliferative disorders." (PMID 30956775, 2019). "Distinct Ras mutations exhibit variable behavior, for instance, the induction of heterozygous KrasG12D/+ expression in the hematopoietic system alone through Mx1-Cre leads to a rapid and highly penetrant myeloproliferative disease (MPD) modeling human MDS/MPN, but does not lead to AML progression." (PMID 38658558, 2024).
ovarian carcinoma (7 papers, 2014 to 2025). A malignant neoplasm originating from the surface ovarian epithelium. "MX1 has been proposed as a therapeutic target in ovarian cancer as studies have identified its role in promoting cell migration and immune evasion." (PMID 40778374, 2025).
Rotavirus infection (7 papers, 2015 to 2022). Infection with any of the rotaviruses. "Similar to the case with WT rotavirus, NSP1 mutant rotavirus infection of WT pMx1-mCherry cell line showed an induction of Mx1-mCherry signal and a subsequent low level of virus spread." (PMID 36000839, 2022). "Consistent with this, Mx1 induction in IEC after rotavirus infection in vivo was more largely dependent on type III IFNs than on type I IFNs61." (PMID 25987506, 2015). "Among them, Mx1 was shown to inhibit viral replication by blocking the transcription of viral RNA, and this protein is considered an important antiviral factor for the protection of the IECs against rotavirus infection." (PMID 34163470, 2021). "Rotavirus infection increased the expression of IFN-β and IFN-λ3 as well as the antiviral factors PKR, Mx1, and RNAseL in PIE cells." (PMID 34163470, 2021). "Of interest, several IFN inducible genes (OAS1, MX1, IL18, IITP3, TAP1, and RSAD2) as well as several cytokines and chemokines (CCL5, CXCL10, CXCL11, IL8, and CCL15) were upregulated by rotavirus infection." (PMID 28210256, 2017).
AIDS (6 papers, 2011 to 2025). A syndrome resulting from the acquired deficiency of cellular immunity caused by the human immunodeficiency virus (HIV). "A potential association of pre-infection gene expression of FAM26F, CXCL10 and MX1 with viral replication in macaques immunized with experimental AIDS vaccines from E1 and E2 was also investigated." (PMID 27902344, 2016). "While neuroinflammation is a cardinal feature of HAD, antiviral responses including induction of IFN-α, MX-1, PRKRA or BST-2 await clarification of their expression in HAD, although several studies indicate the IFN-α might be increased in the brains of HIV/AIDS patients." (PMID 21645334, 2011).
anemia (6 papers, 2015 to 2025). A reduction in the number of red blood cells, the amount of hemoglobin, and/or the volume of packed red blood cells. "As expected, knocking out of Myh9 also caused anemia and pancytopenia in Myh9fl/fl:Mx1-Cre mice, finally leading to an early lethality." (PMID 35740994, 2022). "The Mx1-CreCbfb+/56M mice also developed marked leukocytosis, severe thrombocytopenia, and progressive anemia." (PMID 40763310, 2025). "B6NJ Mx1-Cre; Rasa3 null mice display severe anemia, thrombocytopenia and leukopenia, closely mirroring the B6;129 Mx1-Cre; Rasa3 null phenotype." (PMID 33370780, 2020). "Diseased Mx1-Cre KrasLSL-T58I/+ and Mx1-Cre KrasLSL-P34R/+ mice had significantly elevated blood leukocyte counts, with increased numbers of lymphocytes, neutrophils, and monocytes as well as mild anemia and splenomegaly." (PMID 32990679, 2020). "By contrast, Mx1-Cre KrasLSL-G12D mice on this strain background consistently develop fatal MPN by this age, which is characterized by leukocytosis, progressive anemia with ineffective erythropoiesis, and marked splenomegaly." (PMID 32990679, 2020). "Mx1-cre Aml1-Eto Asxl2fl/WT mice expressing NRASG12D developed worsened anaemia and thrombocytopenia as well as greater circulating GFP/c-Kit double-positive cells and hastened death compared with counterpart Mx1-cre Aml1-Eto Asxl2 WT mice expressing NRASG12D." (PMID 28516957, 2017). "In Mx1-Cre; Rasa3 mutant mice, stress erythropoiesis is established within two weeks of induction of anemia; the spleen is grossly enlarged and its normal nodular architecture is effaced by expansion of the red pulp." (PMID 33370780, 2020).
atherosclerosis (6 papers, 2008 to 2025). A disease characterized by the build-up of fatty material and calcium deposition in the arterial wall resulting in partial or complete occlusion of the arterial lumen. "In atherosclerosis-associated cells, MX1 is involved in the type-I interferon signaling pathway." (PMID 37662558, 2023). "The antiviral function of MX1 is closely related to its role in regulating inflammatory responses, potentially affecting the pathological processes of atherosclerosis." (PMID 40809841, 2025). "Atherosclerosis is a chronic inflammatory disease, and research has found that the MX1 gene may also play a role in the occurrence and development of atherosclerosis." (PMID 40809841, 2025). "The expression of MX1 may lead to endothelial cell damage by regulating the release of inflammatory factors and the activation of immune cells, ultimately affecting the progression of atherosclerosis." (PMID 40809841, 2025). "The expression of MX1 and UBE2L6 was 507.22 ± 342.56 and 96.99 ± 49.92 in the HC+STZ group, respectively, which was significantly higher than others and may be linked to the severity of hyperglycaemia-related atherosclerosis." (PMID 38406276, 2024).
breast tumor (6 papers, 2004 to 2023). "Based on this small verification we performed protein quantification by ELISA for CAPS and MX1 on 79 and 89 breast tumor homogenates respectively." (PMID 25878567, 2015). "Low or defective TAP1 in breast tumors predicts higher risks for developing metastasis and down-regulation of the interferon-stimulated genes IFIT1 and MX1 has been linked to immune evasion mechanisms and tumor progression." (PMID 24870930, 2014).
diabetes (6 papers, 2013 to 2025). "As Mx1, Ifit1, and Oas1 ISGs were increased in young mice, it seems probable that the increase in these ISGs contributed to diabetes onset." (PMID 38487540, 2024). "Mx1 and Spon2 have had altered gene expression due to diabetes in any previous study." (PMID 24199937, 2013).
glioblastoma (6 papers, 2021 to 2024). The most malignant astrocytic tumor (WHO grade IV). "In cancers such as breast and glioblastoma, MX1 expression was elevated compared to normal tissues." (PMID 38972952, 2024).
hepatitis C (6 papers, 2011 to 2023). "Interestingly, the MX1 gene was enriched in the defense response to virus, cellular response to type I interferon, and hepatitis C, influenza A, and measles signaling pathways." (PMID 36713226, 2022). "Functional enrichment analysis revealed that MX1 and RSAD2 were enriched in influenza A and hepatitis C signaling pathways." (PMID 37334926, 2023). "Moreover, KEGG analysis showed that MX1 and RSAD2 were enriched in influenza A and hepatitis C signaling pathways." (PMID 37334926, 2023). "Moreover, MX1 and RSAD2 were enriched in influenza A and hepatitis C signaling pathways." (PMID 37334926, 2023).
lupus nephritis (6 papers, 2016 to 2025). Glomerulonephritis in the context of systemic lupus erythematosus. "This study aims to elucidate the role of Kruppel‐like factor (KLF5) and myxovirus resistance 1 (MX1) in the progression of renal fibrosis in lupus nephritis (LN)." (PMID 37506140, 2023). "Additionally, inhibiting the transcription of MX1 could alleviate renal fibrosis in lupus nephritis." (PMID 38972952, 2024). "Increased MX1 gene expression has been detected in both PBMC and renal intrinsic cells of lupus nephritis patients suggesting its role in the pathogenesis of LN." (PMID 27412348, 2016). "In the comparison of 62 subgroups, the up-regulated gene (PTPRC, MX1) and the down-regulated DEGs (EGR1, MME, RORC, ZBTB16, FKBP5) were verified to have mostly consistent change trends in all Lupus Nephritis vs. Normal Kidneys group with the results of GSE200306." (PMID 39301055, 2024). "Even though MX1, EGR1 and RORC were tested to be DEGs in the glomeruli and tubulointerstitium of primary lupus nephritis patients, in MRL/lpr mice, the difference was not being detected differentially." (PMID 39301055, 2024).
acute lymphoblastic leukemia (5 papers, 2013 to 2019). Leukemia with an acute onset, characterized by the presence of lymphoblasts in the bone marrow and the peripheral blood. "R26PR mice develop fully penetrant T-cell acute lymphoblastic leukemia (T-ALL) with exceptionally short latency (<2 months) when the allele is activated using hematopoietic stem cell-expressing Cre transgenic lines, including Mx1-cre and MMTV-cre." (PMID 27106930, 2016). "As previously reported, we noted that Kit D814V;Mx1-Cre transgenic animals induced with pI:C succumb to a disease that resembles human acute lymphoblastic leukemia (ALL)." (PMID 24788138, 2014). "Cell-type specific methylation patterns between acute myeloid leukemia (AML), myelodysplastic syndrome (MDS), and CD4+ CD8+ T cell acute lymphoblastic leukemia (T-ALL) that develop in Mx-1-Cre;Dnmt3afl/fl mice have been previously reported." (PMID 27677595, 2016). "When R26PR is mated to either of two Cre lines, Mx1-cre or MMTV-cre, mice develop early-onset T-cell acute lymphoblastic leukemia (T-ALL) with median overall survival of 41 and 64 days for R26PR;Mx1-cre and R26PR;MMTV-cre, respectively." (PMID 24046360, 2013).
chronic hepatitis C (5 papers, 2010 to 2023). "Of note, the downregulation of MX1 has been documented in non-responder patients to interferon-based antiviral therapy of chronic hepatitis C virus infection." (PMID 32849840, 2020). "In patients with chronic hepatitis C, the gene expression levels of Rubicon, ISG15, Mx1, and ISG56 were higher than those in non-B, non-C patients." (PMID 32943718, 2020).
Hepatitis (5 papers, 2012 to 2024). Inflammation of the liver. "Because Mx1-Cre;Yapflox/flox mice show slightly better suppression of Yap mRNA and avoid the potential complication of adenovirus-induced hepatitis, all subsequent experiments detailed polyIC-treated Mx1-Cre;Yapflox/flox with Yapflox/flox littermate controls." (PMID 22886419, 2012). "In fact, Mx1 rs2071430 polymorphism, in the promoter region, has been related to Mx1 gene expression, spontaneous viral clearance during acute HCV infection, higher hepatic fibrosis score and hepatitis activity grade, and response to IFN therapy in HCV-monoinfected patients." (PMID 28139728, 2017). "ISGs that were more highly expressed in hepatocytes in the HBeAg‐positive infection phase than in the hepatitis phases, including IFI44, ISG15, IFI44L, MX1, and OAS3, were not correlated with ALT levels." (PMID 39135698, 2024).
liver fibrosis (5 papers, 2015 to 2021). "Taken together, Mof deletion by Mx1-Cre leads to severe liver injury, dysregulation of fatty acid metabolism, and increased liver fibrosis, which are characteristics of steatohepatitis." (PMID 33376138, 2021). "We find that simultaneous deletion of Mof, by Mx1-Cre, in multiple cell compartments in the liver leads to acute liver injury with increase of fat deposition, liver fibrosis, and cell death." (PMID 33376138, 2021). "In the context of ISGs, we previously showed an association between SNP in MX1-88 and progression of HCV-induced liver fibrosis, the current study confirmed that these genetic variants dramatically impact the mRNA expression of MX1." (PMID 27135246, 2016). "In conclusion, Mx1 and OAS1-2 polymorphisms were associated with the severity of liver disease in HIV/HCV-coinfected patients, suggesting a significant role in the progression of hepatic fibrosis." (PMID 28139728, 2017). "In conclusion, Mx1 and OAS1-2 polymorphisms were associated with the severity of liver disease in patients coinfected with HIV and HCV, suggesting that these polymorphisms might play a significant role in the progression of hepatic fibrosis." (PMID 28139728, 2017).
measles (5 papers, 2022). A highly contagious viral infection caused by the measles virus. "MX1 also has antiviral properties against other viruses, including influenza A, measles, and type-3 parainfluenza viruses." (PMID 36211429, 2022).
multiple sclerosis (5 papers, 2011 to 2023). A progressive autoimmune disorder affecting the central nervous system resulting in demyelination. "Myxovirus A (MxA), a protein encoded by the MX1 gene with antiviral activity, has proven to be a sensitive measure of IFNβ bioactivity in multiple sclerosis (MS)." (PMID 21886806, 2011).
myelodysplastic syndrome (5 papers, 2016 to 2022). A clonal hematopoietic disorder characterized by dysplasia and ineffective hematopoiesis in one or more of the hematopoietic cell lines. "Mutations at proline 95 substituted with histidine (Srsf2P95H) were sufficient to induce in myelodysplastic syndromes (MDS) in inducible Mx1-Cre Srsf2P95H/WT knock-in mice." (PMID 32372053, 2020).
Obesity (5 papers, 2013 to 2025). Accumulation of substantial excess body fat. "To test the role of myeloid cell intrinsic Jak2–Stat3 signaling inducing obesity-associated insulin resistance, we generated control (Mx1-Cre/Jak2+/+) mice and mice with the hematopoietic cell ablation of Jak2 (Mx1-Cre/Jak2−/−)." (PMID 40801626, 2025). "Other nominally significant associations were established between WHOCS scales and: IFNL4 rs12979860, ACEIs, obesity, ARA-II, HCP5 rs2395029, ACE rs1799752, DPP4 rs17574, HMOX1 rs2071746, IL10 rs1800896, IL6 rs1818879, NFKB1 rs28362491, and MX1 rs469390." (PMID 35636966, 2022). "A number of host factors including SNPs of interferons IL28A, IL28B, IL29, interferon-γ, MBL, IL -10, IL-18, CTLA4, TRAIL, TGF-β, MX1, Osteopontin, LMP7, OAS1 genes, insulin resistance, obesity and ethnicity, have been found to modulate the treatment response." (PMID 24079723, 2013).
Splenomegaly (5 papers, 2017 to 2023). Abnormal increased size of the spleen. "Of note, longitudinal evaluation of recipient mice transplanted with Mx1-cre Asxl2fl/fl mice up to 52 weeks failed to reveal any Asxl2-deficient mice to have developed increased white blood counts, splenomegaly or expansion of HSPCs." (PMID 28516957, 2017). "Consistent with our previous findings, Mx1-Cre:FLT3ITD/ITD, developed leukocytosis and this progressed to a rapidly fatal AML accompanied by splenomegaly and immature blasts in PB and BM whereas control mice did not develop AML." (PMID 36739348, 2023).
triple-negative breast carcinoma (5 papers, 2018 to 2024). An invasive breast carcinoma which is negative for expression of estrogen receptor (ER), progesterone receptor (PR), and human epidermal growth factor receptor 2 (HER2). "In our study investigating the effects of MIA-602 on HCC-1806 and MX-1 human triple negative breast cancers xenografted into nude mice, MIA-602 treatment at a concentration of 5 μg/day for 5 weeks significantly inhibited mean tumor volume of HCC-1806 tumors and of MX-1 tumors compared to controls." (PMID 38588464, 2024).
asthma (4 papers, 2022 to 2024). "Classifying the 48 subjects into either mold-sensitized (sIgE to mx1 ≥ 0.35 kUA/L) subjects (n = 12) or non-mold-sensitized (sIgE to mx1 < 0.35 kUA/L) subjects (n = 36) showed that respiratory symptoms, including asthma, predominated in the mold-sensitized (mx1-positive) group." (PMID 35392213, 2022). "Significant associations between mold exposure and asthma were analyzed in detail by subdividing the exposed and non-exposed group into asthmatics and non-asthmatics with regard to CC16, tIgE as well as mx1 and sx1 sIgE." (PMID 35392215, 2022). "The proportion of mx1-positive subjects was significantly higher in those with asthma compared to the non-asthmatics (46% vs. 4%), and the proportion of sx1-positive subjects was also significantly higher among the asthmatics (67 vs. 33%)." (PMID 35392213, 2022).
colorectal cancer (4 papers, 2015 to 2024). A primary or metastatic malignant neoplasm that affects the colon or rectum. "Research on colorectal carcinomas has revealed that the expression level of MX1 in tumors with lymph node metastases (UICC stage III) is higher than that in tumors without lymph node metastases (UICC stage II)." (PMID 38972952, 2024). "In the responders, colorectal cancers with high MX-1 tend to be more invasive with more metastases." (PMID 38304289, 2023).
Down syndrome (4 papers, 2014 to 2024). "In addition, an association between AA and an interferon‐inducible p78 protein gene (MX1), which maps to the distal part of the Down syndrome critical region, has been reported." (PMID 36321512, 2023). "For example, four IFN receptor genes (IFNAR1, IFNAR2, IFNGR2, and IL10RB) and two IFN-stimulated genes (MX1 and MX2) are triplicated in Down syndrome, and individuals with Down syndrome exhibit hypersensitivity to type I IFN (IFN-I)." (PMID 38540156, 2024).
encephalitis (4 papers, 2020 to 2026). An acute inflammatory process affecting the brain parenchyma. "Across multiple feature selection algorithms, ACVR2B and MX1 were reproducibly prioritized as immune-associated candidate genes and were consistently downregulated in anti-NMDAR encephalitis samples, showing negative correlations with neutrophil infiltration." (PMID 41596688, 2026).
idiopathic interstitial pneumonia (4 papers, 2017 to 2022). A class of diffuse lung diseases that typically affect the pulmonary interstitium, although some also have a component affecting the airways (for instance, Cryptogenic organizing pneumonitis). "Interestingly, the increased expression of MX1 autoantibody in serum is associated with a good prognosis in patients with idiopathic interstitial pneumonia, suggesting that the inhibition of MX proteins is a possible strategy for preventing fibrotic lung diseases." (PMID 34361872, 2021). "We found that a higher anti-MX1 autoantibody level was a significant predictor of a good prognosis in patients with non-IPF idiopathic interstitial pneumonias." (PMID 35391716, 2022).
lung adenocarcinoma (4 papers, 2017 to 2024). A carcinoma that arises from the lung and is characterized by the presence of malignant glandular epithelial cells. "The IFI6 protein plays a central role in resistance to apoptosis in various cancer types, and MX1 protein levels are increased in lung adenocarcinoma." (PMID 35354498, 2022).
myeloid leukemia (4 papers, 2017 to 2025). A clonal proliferation of myeloid cells and their precursors in the bone marrow, peripheral blood, and spleen. "These conditional Llgl1 knockout animals were intercrossed with Mx1-Cre+ animals and a conventional (straight) MLL-AF9 knock-in model that develops myeloid leukemia with a median latency of 5-6 months." (PMID 37587260, 2023). "In line with the previous report, BM from NrasG12D/G12D; Mx1‐Cre+; Golga7WT mice displayed an expanded Lin−Kit+ (LK) cell population as well as common myeloid progenitor (CMP) (LK/CD16/32−CD34+), representing a typical committed myeloid leukemia phenotype." (PMID 40091521, 2025).